RBKS (ribokinase)
Description:
Catalyzes the phosphorylation of ribose at O-5 in a reaction requiring ATP and magnesium. The resulting D-ribose-5-phosphate can then be used either for sythesis of nucleotides, histidine, and tryptophan, or as a component of the pentose phosphate pathway.
Synonyms: RK; RBSK; DKFZp686G13268
Tractability: Small molecule: a structure with a bound ligand is known; it has a high-quality binding pocket. PROTAC: its protein half-life has been measured.
Gene: Protein-coding gene on chromosome 2 (27,780,857 to 27,890,681, reverse strand). Ensembl gene ENSG00000171174.
Subcellular location: Cytoplasm; Nucleus
Subcellular location (Human Protein Atlas): Cytosol; Nucleoplasm
Pathways (Reactome):
Metabolism: Pentose phosphate pathway
Gene Ontology:
Molecular function: identical protein binding; protein binding; ribokinase activity; ATP binding; kinase activity
Biological process: pentose-phosphate shunt; carbohydrate phosphorylation; D-ribose catabolic process; D-ribose metabolic process
Cellular component: cytoplasm; cytosol; nucleus
Genetic constraint (gnomAD): Loss-of-function variants: 19 observed, 21.78 expected, observed/expected ratio (o/e) 0.87, 90% interval 0.61 to 1.28. The upper end of that interval is the gene's LOEUF score, 1.28, which puts it in group 5 of 6, group 1 being the genes least tolerant of losing a copy. Missense variants: 280 observed, 318.71 expected, observed/expected ratio (o/e) 0.88, 90% interval 0.8 to 0.97. Synonymous variants: 103 observed, 120.21 expected, observed/expected ratio (o/e) 0.86, 90% interval 0.73 to 1.01.
Homologues: Orthologues: chimpanzee RBKS (99% identical), macaque RBKS (98% identical), pig RBKS (90% identical), rabbit RBKS (89% identical), guinea pig RBKS (88% identical), mouse Rbks (86% identical), rat Rbks (81% identical), dog RBKS (73% identical), tropical clawed frog rbks (69% identical), zebrafish rbks (65% identical), Drosophila melanogaster CG13369 (42% identical), Caenorhabditis elegans F07A11.5 (41% identical), and 1 more. Paralogues in human: ADK (19% identical), KHK (18% identical), TMEM256 (8% identical).
Diseases named in the same sentence as RBKS in open-access papers:
RBKS is named in the same sentence as 10 diseases in open-access papers, as found by Europe PMC text mining. Sharing a sentence is not in itself a finding about the gene and the disease. The quoted sentences say what the papers report.
hepatocellular carcinoma (1 paper, 2019). A malignant tumor that arises from hepatocytes. "This indicates that SPP2, LECT2, CPS1, and Ribokinase exert tumor suppressive effects in hepatocellular carcinoma." (PMID 31849319, 2019). "SPP2 was co-expressed with LECT2, CPS1, and Ribokinase in hepatocellular carcinoma." (PMID 31849319, 2019).
Insulin resistance (1 paper, 2024). Increased resistance towards insulin, that is, diminished effectiveness of insulin in reducing blood glucose levels. "MSR1, KYNU, and RBKS, but not SMPD1, were associated with metabolic and liver dysfunction markers, while SCARA5, TNFRSF12A, SMOC2, but not GDF-8, were associated with insulin resistance markers." (PMID 39407757, 2024). "RBKS, but not SMPD1, was associated with metabolic and liver dysfunction markers, while SCARA5, TNFRSF12A, and SMOC2, but not GDF-8, were associated with insulin resistance markers, and steatosis grade in the OB group." (PMID 39407757, 2024).
metastatic tumors (1 paper, 2024). "The genes that were upregulated in the monosomy 3/metastatic tumors (PFKP, NUP88) exhibited an average fold change (FC) of 2.06 ± 0.82, whereas the downregulated genes (INSR, RBKS, and ZBTB20) differed by an average of −1.87 ± 0.44-fold." (PMID 38673877, 2024).
myositis (1 paper, 2013). "After performing QRT-PCR analysis on the genes related to the internal production of D-ribose (via AMP catabolism), we found that the first enzyme utilizing ingested D-ribose, RBKS, was expressed at very low basal levels in both healthy and myositis mice." (PMID 23785461, 2013).
pancreatic cancer (1 paper, 2015). "RBSK (ribokinase) is an important component of the first step of ribose metabolism; however, its elevated expression was demonstrated in livers of patients having pancreatic cancer metastasis." (PMID 25901992, 2015).
liver (1 paper, 2024). "Interestingly, correlation analysis in PWS significantly associated Ribokinase (RBKS), KYNU, Macrophage Scavenger Receptor 1 (MSR1), and SMPD1 with metabolic and liver dysfunction markers, such as transaminases, triglycerides, glycemia, and glycated hemoglobin." (PMID 39407757, 2024).
RBKS also shares sentences with these, for which no sentence is quoted: Anorexia (1 paper); liver dysfunction (1); steatosis (1); tumor (1).